LPAR2 (lysophosphatidic acid receptor 2)
Diseases named in the same sentence as LPAR2 in open-access papers (continued):
Sharing a sentence is not in itself a finding about the gene and the disease.
leukemia (2 papers, 2021 to 2022). A malignant (clonal) hematologic disorder, involving hematopoietic stem cells and characterized by the presence of primitive or atypical myeloid or lymphoid cells in the bone marrow and the blood. "However, LPAR2 expression was lower in kidney cancer, leukemia, lung cancer, lymphoma and sarcoma tissues than in normal control tissues." (PMID 35241179, 2022).
lung carcinoma (2 papers, 2022). "On analyzing the mRNA expression levels of LPAR2 in pan-cancer and normal tissues using Oncomine, we found that LPAR2 expression was higher in bladder, brain and central nervous system (CNS), breast, colorectal, kidney, and lung cancers and lymphoma than in normal control tissues." (PMID 35241179, 2022).
ovarian tumor (2 papers, 2010 to 2024). "Experimental data evidenced that the stimulation of LPAR2–3 by LPA results in VEGF production in ovarian tumor cells." (PMID 39062979, 2024). "In another experimental study, the proliferative activity of human ovarian tumor cells was correlated to the activation of LPAR2 and LPAR3 signaling pathways but not LPAR1." (PMID 39062979, 2024).
renal carcinoma (2 papers, 2022 to 2023). A carcinoma arising from the epithelium of the renal parenchyma or the renal pelvis. "LPA promotes the interaction of GNA12 and EFA6 through LPAR2 and activates the ADP-ribosylation factors 6-based pathway, consequently promoting the invasion of renal cancer cells." (PMID 37426201, 2023).
Anxiety (1 paper, 2021). Intense feelings of nervousness, tension, or panic often arise in response to interpersonal stresses. "Further, zero-maze behavior would agree with lower anxiety of LPAR2−/− mice and argue against an anxiety-dependent suppression of corner visiting activity." (PMID 32468095, 2021).
brain injury (1 paper, 2021). Acute and chronic (see also brain INJURIES, CHRONIC) injuries to the brain, including the cerebral hemispheres, CEREBELLUM, and brain STEM. "In traumatic brain injury, LPA activity is increased due to upregulated expression of LPAR1, LPAR2, and LPAR." (PMID 34666785, 2021).
breast tumors (1 paper, 2023). "Significantly, Infliximab treatment also decreased the mRNA for LPAR2 in breast tumors." (PMID 38201482, 2023).
enteropathy (1 paper, 2024). "Our study, however, also reveals the importance of LPAR2 in the development of tissue inflammation associated with enteropathy." (PMID 37816857, 2024). "Our study provides the first demonstration that LPAR2 has a role in maintaining intestinal mucosal integrity after NSAID exposure-induced enteropathy and regulates the inflammatory response associated with ulceration." (PMID 37816857, 2024). "In this study, we investigated whether LPAR2 signaling was implicated in the development of NSAID-induced small intestinal injury (enteropathy), another major complication of NSAID use." (PMID 37816857, 2024). "Taken together, tissue inflammation associated with enteropathy developed more rapidly in the absence of LPAR2, in particular, due to earlier recruitment and activation of neutrophils." (PMID 37816857, 2024). "In comparison, in Lpar2−/− mice shortening of the intestine, development of mucosal erosions and tissue infiltration of neutrophils started earlier, as early as 6 h after the administration of IND, suggesting that deletion of Lpar2 promoted the development of enteropathy." (PMID 37816857, 2024). "LPAR2 activation, therefore, appears to be a double-edged sword in NSAID enteropathy, which protects the mucosa but at the same time, enhances the accompanying inflammatory reaction." (PMID 37816857, 2024). "Since the lack of LPAR2 promoted the development of enteropathy, DBIBB was expected to induce mucosal protection, and the severity of IND-induced damage was assessed only at a later time point, 24 h post-dose." (PMID 37816857, 2024). "Therefore, selective LPAR2 activation has both mucoprotective and proinflammatory effects in the context of NSAID enteropathy." (PMID 37816857, 2024). "Administration of a selective LPAR2 agonist DBIBB (1, 10 mg/kg, i.g., twice at 24 h and 30 min before IND treatment) dose-dependently reduced mucosal injury and neutrophil activation in enteropathy, but it also enhanced IND-induced elevation of several proinflammatory chemokines and cytokines." (PMID 37816857, 2024). "Finally, it should be noted that although our study focused on LPAR2, other types of LPARs may also have effect on NSAID enteropathy." (PMID 37816857, 2024). "Our study also shows that IND can reduce the plasma activity of ATX and the intestinal expression of Lpar2 mRNA earlier than the enteropathy develops, indicating that suppression of the ATX-LPA-LPAR2 axis may contribute to the initial topical damaging effect of IND to the mucosa." (PMID 37816857, 2024). "Moreover, both inhibition of ATX activity and LPAR2 expression preceded the development of mucosal damage and inflammation, implying that downregulation of the ATX-LPA-LPAR2 axis may be an early event in the pathogenesis of IND-induced enteropathy." (PMID 37816857, 2024). "Here we showed for the first time that LPAR2 has a pivotal role in maintaining intestinal mucosal integrity against NSAIDs, because the lack of LPAR2 accelerates the development of NSAID enteropathy, whereas selective activation of LPAR2 reduces the severity of intestinal mucosal injury." (PMID 37816857, 2024). "Our results provide further evidence for the mucosal protective property of LPAR2 and demonstrate for the first time that selective activation of LPAR2 by DBIBB mitigates NSAID-induced small intestinal injury, whereas lack of LPAR2 accelerates the development of enteropathy." (PMID 37816857, 2024).
gastropathy (1 paper, 2024). "The development and use of novel, highly selective LPAR ligands and targeted gene knockout animal models have also allowed to identify LPAR2 as a central regulator of protection against γ-irradiation-induced intestinal injury, NSAID-induced gastropathy and toxin-induced diarrheas." (PMID 37816857, 2024).
hematoma (1 paper, 2022). A hematoma is a collection of blood from a vascular structure into an extravascular space. "Mice lacking Lpar2 are grossly normal, but an increased incidence of perinatal frontal hematoma is observed in Lpar1/Lpar2 double KO (Lpar1−/−/Lpar2−/−) mice compared with Lpar1−/− mice, indicating a modest role of LPA2 in vascular development." (PMID 35883686, 2022).
Hyperammonemia (1 paper, 2023). An increased concentration of ammonia in the blood. "Then, we evaluated the therapeutic potential effects of HA130 in TAA-induced acute liver injury and found that hyperammonemia altered some of the mRNA expressions of LPARs in astrocytes (i.e., LPAR2 and 6) together with an increase in the astrocyte volume." (PMID 37528089, 2023).
itch (1 paper, 2024). "In the present study, we show a segregated localization of LPAR5 in peripheral sensory neurons and LPAR2 in cortical and thalamic neurons and opposing effects of deletion of either LPAR5 or LPAR2 on HCQ-evoked itch responses." (PMID 39125747, 2024).
liver disease (1 paper, 2026). "This aligns with LPAR2’s established pro-fibrotic/pro-inflammatory roles in liver disease." (PMID 41056021, 2026).
mastitis (1 paper, 2023). Inflammation of breast tissue during lactation or postpartum due to an obstructed duct or infection. "In the MGI database, we found one gene disruption (Mfge8) and five transgenic mouse models for Lao1, Enpp2, Lpar1, Lpar2, and Lpar3 that resulted in abnormal mammary gland physiology and were also associated with mastitis." (PMID 36759924, 2023).
myocardial infarction (1 paper, 2025). Gross necrosis of the myocardium, as a result of interruption of the blood supply to the area, as in coronary thrombosis. "Our research group has previously found that the expression of LPA2 in the heart after myocardial infarction is increased, mainly from ECs, and the results showed that the cardiac vascular permeability is significantly increased in Lpar2−/− mice." (PMID 39927163, 2025).
Nance-Horan syndrome (1 paper, 2020). A syndrome characterized by the association in male patients of congenital cataracts with microcornea, dental anomalies and facial dysmorphism. "An interaction network analysis of the top 100 DM CpG sites showed five common regulator genes: nemo-like kinase (NLK), calcium/calmodulin-dependent protein kinase 1 (CAMKK1), lysophosphatidic acid receptor 2 (LPAR2), caspase 1 (CASP1), and Nance-Horan syndrome (NHS)." (PMID 32605309, 2020).
pneumonia (1 paper, 2024). An acute, acute and chronic, or chronic inflammation focally or diffusely affecting the lung parenchyma, caused by an infection in one or both of the lungs (by bacteria, viruses, fungi, or mycoplasma.). "It is noteworthy that in previous studies LPAR1 rather than LPAR2 was shown to promote neutrophil migration in pneumonia and production of the neutrophil chemoattractant IL-8 in human bronchial epithelial cells." (PMID 37816857, 2024).
Sepsis (1 paper, 2022). Sepsis is defined as life-threatening organ dysfunction caused by a dysregulated host response to infection. "Therefore, both LPAR5 and LPAR1, but not LPAR2, mediate to some extent the pathogenic effects of ATX/LPA in experimental sepsis." (PMID 35887265, 2022).
triple-negative breast carcinoma (1 paper, 2023). An invasive breast carcinoma which is negative for expression of estrogen receptor (ER), progesterone receptor (PR), and human epidermal growth factor receptor 2 (HER2). "LPAR1 and LPAR6 gene expression were highest in ER+HER2– (estrogen-receptor-positive, human-epidermal-growth-factor-receptor-negative) tumors and lowest in TNBC (triple negative breast cancer) tumors in all three cohorts, while this pattern was reversed for LPAR2 and LPAR3 (all p < 0.001)." (PMID 37372960, 2023).
Venous thrombosis (1 paper, 2025). Formation of a blood clot (thrombus) inside a vein, causing the obstruction of blood flow. "By gross observation, venous thrombosis was formed in both the WT-DVT group and the Lpar2-cKO-DVT group." (PMID 39927163, 2025).
tumor (38 papers, 2004 to 2026). "Higher mRNA expression of LPAR2 was associated with better OS in HNSC tumor stage 2–4 (stage 2, HR = 0.45 [0.2–0.99], P = 0.042; stage 3, HR = 0.35 [0.14–0.88], P = 0.019; stage 4, HR = 0.55 [0.38–0.79], P = 0.00094)." (PMID 35241179, 2022). "The findings suggested that high LPAR2 expression was associated with advanced tumor stages, high tumor grades, and lymph node metastasis in patients with KIRC." (PMID 35241179, 2022). "Analyses of publicly available data on breast cancer have also shown that LPAR1, 4 and 6 gene expression negatively correlate with tumour aggressiveness, while on the contrary, high LPAR2 expression is associated with increased tumour grade and reduced patient survival." (PMID 38607068, 2024). "Resistance to cisplatin in this tumour type is also potentiated by hypoxia, which increases the expression of both LPAR2 and LPAR3." (PMID 38607068, 2024). "The correlation between LPAR2 expression and gene markers of tumor immune infiltrates was analyzed using TIMER and GEPIA." (PMID 35241179, 2022). "The expression of LPAR2 in pan-cancers was analyzed using the Online Cancer Microarray Database (Oncomine), Tumor Immune Estimation Resource (TIMER), and UALCAN databases." (PMID 35241179, 2022). "Given that immunotherapy mainly targets the tumor immune microenvironment, we analyzed the effects of LPAR2 on tumor prognosis and immune infiltration of HNSC and KIRC in this study." (PMID 35241179, 2022). "LPAR2 is correlated with tumor immune cell infiltration and is a valuable prognostic biomarker for HNSC and KIRC." (PMID 35241179, 2022). "For the criterion of tumor stage, we found that LPAR2 expression was significantly higher in patients with stage 1–4 HNSC than in patients in the control group (P < 0.001)." (PMID 35241179, 2022). "Using KM plotter, we found that high LPAR2 expression was associated with improved prognosis in patients with HNSC with advanced tumor stages and high tumor grades." (PMID 35241179, 2022). "We found that LPAR2 expression had a positive correlation with tumor purity in HNSC and KIRC, the infiltration of B cells and CD4 + T cells in HNSC, and the infiltration of B cells, CD4 + T cells, neutrophils, and DCs in KIRC." (PMID 35241179, 2022). "In patients with KIRC, LPAR2 expression was upregulated in patients with tumor stages 3 and 4 (P < 0.001)." (PMID 35241179, 2022). "This study aims to explore the correlation between LPAR2 expression with tumor prognosis and immune infiltration in pan-cancers." (PMID 35241179, 2022). "A previous study indicated that LPAR2 was correlated with a higher rate of lymphatic and venous invasion, lymphatic metastasis and the resulting tumor stage in diffuse-type gastric cancer." (PMID 23426604, 2013). "Moreover, the R software program was applied for validation of expression and prognostic value of LPAR2 in tumor patients in the Cancer Genome Atlas (TCGA) dataset and the Gene Expression Omnibus (GEO) database." (PMID 35241179, 2022). "Furthermore, the correlation between LPAR2 expression and tumor immune infiltration was examined using TIMER." (PMID 35241179, 2022). "In addition, we analyzed the correlation between LPAR2 and tumor-infiltrating immune cells in the microenvironment of pan-cancer using TIMER and GEPIA." (PMID 35241179, 2022). "Moreover, LPAR2 is more important for regulating tumor purity and the infiltration of B cells and CD4 + T cells in HNSC as well as the infiltration of neutrophils and DCs in KIRC." (PMID 35241179, 2022). "LPAR2 expression was evaluated in tumor and normal tissues in multiple cancer types." (PMID 35241179, 2022). "Furthermore, to investigate the role of LPAR2 in the regulation of tumor immunology in HNSC and KIRC, we analyzed the relationship between LPAR2 expression and marker genes of immune cells." (PMID 35241179, 2022). "The expression levels of LPAR2 have a critical role in carcinogenesis and during tumor progression." (PMID 32605309, 2020).
tumor (continued). "Microarray analysis in these livers shows that among the different LPARs, only LPAR2 is downregulated upon ATX deletion from the liver tissue suggesting that LPAR2 may be responsible for the tumor-promoting role of LPA in that model." (PMID 31652837, 2019). "Interestingly, in our study LPAR2 was shown to be a marker of the immune low tumor subtype." (PMID 31049165, 2019). "In renal cancer cells, LPAR2 activates MAPK/NF-κβ signalling to induce cytokine expression and promote tumour growth and metastasis." (PMID 38607068, 2024). "While almost all naive CD8+ T cells express LPAR2, LPAR5, and LPAR6, we next wanted to analyze the expression of these receptors on tumor-infiltrating CD8+ T cells." (PMID 37655662, 2023). "Enpp2 promotes tumor cell dispersal, migration, and metastasis through LPAR1 and T cell motility through LPAR2." (PMID 37052764, 2023). "With both tumor cells and TAM expressing similar levels of LPAR1 and LPAR2, LPAR3 was predominantly expressed in tumor cells, while LPAR5 and LPAR6 were selective for TAM." (PMID 32397679, 2020). "In tumor cells, LPAR1, LPAR2, and LPAR3 are the major subtypes, while LPAR5 and LPAR6 are expressed only at very low levels in a subset of patients, if at all." (PMID 30353652, 2019). "LPA in ascites apparently targets tumor cells and TAMs via specific receptors, since LPAR1 and LPAR2 are expressed at similar levels by both cell types, LPAR3 is selective for tumor cells, LPAR5 and LPAR6 for TAMs." (PMID 27215396, 2016). "Nodular tumours of the liver are induced by LPA signalling, and this could be driven, at least in part, by LPA binding to LPAR2, which activates p38 signalling to promote abnormal leptin expression and liver carcinogenesis." (PMID 38607068, 2024). "In a seminal murine tumor study examining the overexpression of ATX and LPAR1, LPAR2, and LPAR3 in a mouse mammary tumor virus model, the LPAR2-overexpressing model had the highest tumorgenicity rate at 52.8%, followed by ATX at 50.0%, LPAR3 at 42.3%, and LPAR1 at 32.0%." (PMID 37372960, 2023). "Signals of LPA through LPAR2 have been reported to have pro-T cell function, which suggests that LPA signalling may improve the immune response against tumours." (PMID 34722305, 2021). "Intriguingly, different LPAR subtypes may have opposing functions in tumor cells, as described, for instance, for the role of LPAR1 and LPAR2 in the LPA‐triggered migration of pancreatic cancer cells." (PMID 30353652, 2019). "It is interesting that ATX, LPAR1, and LPAR5 are higher in the immune-high tumor (Cd14-, Cd68-, Cd164-, and Cd3E-high) group, but LPAR2.3 are higher in the immune-low group, suggesting the complex regulatory roles of the ATX–LPA axis in the tumor–immune system interaction." (PMID 31658655, 2019). "Further limitations of the present study are the lack of evidence on protein level for both ATX and LPAR2 expression upon irradiation and the lack of translational evidence, such as preliminary data from patient tumor samples, to validate our in vitro findings." (PMID 39338222, 2024). "Interestingly, the rest of the LPARs (LPAR1, LPAR3–5) are decreased in the HCC liver as compared to adjacent normal tissue, suggesting that LPAR2 and LPAR6 are probably expressed in the tumor whereas the rest LPARs are expressed in the surrounding microenvironment." (PMID 31652837, 2019). "Furthermore, the enhanced expression of LPAR2 and LPAR3, but none of S1PRs, was characteristic for the immune low tumor subtype." (PMID 31049165, 2019).